CHMP2B (charged multivesicular body protein 2B)
Diseases named in the same sentence as CHMP2B in open-access papers (continued):
Sharing a sentence is not in itself a finding about the gene and the disease.
Parkinson disease (12 papers, 2009 to 2025). A progressive degenerative disorder of the central nervous system characterized by loss of dopamine producing neurons in the substantia nigra and the presence of Lewy bodies in the substantia nigra and locus coeruleus. "Mutations in the CHMP2B gene, which is located on chromosome 3 and encodes the charged multivesicular body protein 2b, have been linked with FTD accompanied by parkinsonism occurring later during the course of the disease." (PMID 40722695, 2025). "Here the authors show that disruption of an interaction between ESCRT-III member CHMP2B and α-synuclein by a peptide inhibitor mitigates neurodegeneration in Parkinson’s disease models." (PMID 37076542, 2023). "Four other less common genetic links reported in familial FTD with parkinsonism cases are—chromatin modifying protein 2B (CHMP2B), transactive response DNA-binding protein (TARDBP), valosin-containing protein (VCP), and fused-in-sarcoma (FUS) genes." (PMID 33250855, 2020). "In fact, CHMP2B immunoreactive granules are observed as granulovacuolar degeneration in the brains of Parkinson’s disease, incidental Lewy body disease and Alzheimer’s disease (AD) patients." (PMID 26373282, 2015). "Previously, mutations in SOD1, ANG, FUS/TLS, TARDBP and CHMP2B have been identified in patients with a range of clinical phenotypes, including combinations of FTD, Parkinson’s disease, and ALS." (PMID 23155438, 2012). "Moreover, parkinsonism can be involved in cases with TDP-43, ANG, OPTN, and CHMP2B mutations." (PMID 26213621, 2015). "In addition, mutations in the endo-lysosomal trafficking machinery have been implicated in neurodegenerative disorders including ALS and FTD (CHMP2B, FIG4, VAPB, and VCP) and defects in retrograde trafficking increase the risk for Parkinson's disease (VPS35)." (PMID 26357016, 2015). "Mutations in CHMP2B have been shown to cause ALS, FTD (with or without parkinsonism) and presenile dementia." (PMID 29479499, 2018).
dementia (10 papers, 2011 to 2025). Loss of intellectual abilities interfering with an individual's social and occupational functions. "No other pathogenic mutation in genes known to be associated with neurodegenerative diseases, and/or rare genetic causes of dementia, such as mutations in CHMP2B, FUS, TARDBP, SQSTM1 and VCP have been identified." (PMID 27632209, 2016). "Among the 2384 unique gene correlates of Gsto1 expression in hippocampus are 128 genes that share a high co-incidence of literature citations—24 of which are known to be associated with AD or dementia, including well studied candidates Chmp2b, Optn, Dlst, Sod2, and Acat1." (PMID 26829228, 2016). "Despite being a rare cause of dementia, recent advances in our understanding of the molecular basis of CHMP2B mutations indicate that the mechanisms involved may be broadly relevant to neurodegenerative processes." (PMID 21222599, 2011). "In support of this model, polymorphisms in the ESCRT-III proteins CHMP2B and CHMP4B are associated with dementia and cataracts, respectively, both of which are associated with mutations in lamin A/C37,43-45." (PMID 30139939, 2018).
Alzheimer disease (5 papers, 2012 to 2022). A progressive, neurodegenerative disease characterized by loss of function and death of nerve cells in several areas of the brain leading to loss of cognitive function such as memory and language. "CHMP2B is a marker for granulovacuolar degeneration (GVD) bodies in the Alzheimer’s disease (AD) brain." (PMID 36330465, 2022). "Among them, mutations in charged multivesicular body protein 2B (CHMP2B) are especially interesting, as they are highly pathogenic in FTD linked to chromosome 3 (FTD-3) and also found in some ALS cases and patients with early-onset Alzheimer’s disease (AD)." (PMID 36414997, 2022).
sarcoma (4 papers, 2012 to 2018). A usually aggressive malignant neoplasm of the soft tissue or bone. "Sanger sequencing was used to screen these subjects for mutations in the coding regions of superoxide dismutase-1 (SOD1), angiogenin (ANG), fused in sarcoma/translated in liposarcoma (FUS/TLS), TAR DNA-binding protein 43 (TARDBP), and multivesicular body protein 2B (CHMP2B)." (PMID 23155438, 2012).
colorectal cancer (3 papers, 2022 to 2024). A primary or metastatic malignant neoplasm that affects the colon or rectum. "However, the role of CHMP2B, BID and CHMP6 in colorectal cancer have not been reported yet, which may provide new biomarkers for future research on the relationship between necrosis and colorectal cancer." (PMID 35783272, 2022).
motor neuron disease (3 papers, 2011 to 2025). "Finally, we collate the current data on CHMP2B missense mutations, which have been reported in FTD and motor neuron disease." (PMID 21222599, 2011).
Paget disease of the bone (3 papers, 2015 to 2022). "Other uncommon mutations have been identified in the valosin-containing protein (VCP) gene, which cause inclusion body myopathy with Paget disease of bone and FTD, and in the charged multivesicular body protein 2B (CHMP2B) gene, involved in the endosomal–lysosomal pathway." (PMID 26388768, 2015).
proteinopathies (3 papers, 2018 to 2025). "In addition, heightened TE expression occurs in the context of tauopathies and a distinct FTD-related proteinopathy because of pathogenic CHMP2B variation." (PMID 36446586, 2023).
Cognitive impairment (2 papers, 2021 to 2022). Abnormal cognition is characterized by deficits in thinking, reasoning, or remembering. "In this study, we generated two additional FTLD mouse models harboring mutation of TDP43 (TDPN267S-KI) or CHMP2B (CHMP2BQ165X-KI), which reproduced human FTLD-TDP or FTLD-UPS pathology and cognitive impairment." (PMID 34130995, 2021).
dementia with Lewy bodies (2 papers, 2015 to 2021). "Interestingly, reduced levels of CHMP2B were found in a transgenic mouse model of PD and brain samples of patients with PD and dementia with Lewy bodies (DLB) associated with α-syn accumulation." (PMID 34298912, 2021).
Dystonia (2 papers, 2025). An abnormally increased muscular tone that causes fixed abnormal postures. "Common movement disorders in patients with CHMP2B mutations include myoclonus, dystonia, and stereotypical behavior, while Richardson’s syndrome and CBS represent rare manifestations." (PMID 40722695, 2025).
psoriasis (2 papers, 2022 to 2025). An autoimmune condition characterized by red, well-delineated plaques with silvery scales that are usually on the extensor surfaces and scalp. "In contrast, the role of charged multivesicular body protein 2B (CHMP2B) in psoriasis remains unconfirmed." (PMID 40906403, 2025). "The strong link between ELOVL4 and IL36B, CDK7, CHMP2B, and S100A13 was also evident in RNA-Seq data sets of psoriasis lesional skin." (PMID 35900871, 2022).
Apathy (1 paper, 2025). Apathy is a quantitative reduction of interest, motivation and the initiation and persistence of goal-directed behavior, where often the accompanying emotions, thoughts, and social interactions are also diminished. "Progranulin (PGRN) mutations correlated with apathy and hallucinations, microtubule-associated protein tau (MAPT) mutations with disinhibition, and charged multivesicular body protein 2B (CHMP2B) with social impairments." (PMID 40649976, 2025).
Brain atrophy (1 paper, 2017). Partial or complete wasting (loss) of brain tissue that was once present. "We have shown previously that these particular brain regions harbour inclusion pathology, and these findings are consistent with brain volume changes observed by MRI in CHMP2B-FTD patients, suggesting that brain atrophy is occurring in CHMP2BIntron5 mice." (PMID 28093491, 2017).
breast carcinoma (1 paper, 2024). "The univariate and multivariate Cox analysis further confirmed that CHMP2B was a detrimental prognostic factor in breast cancer." (PMID 38169571, 2024). "In our study, we applied IHC analysis based on tissue microarray to further validate the role of CHMP2B in breast cancer." (PMID 38169571, 2024).
cardiomyopathy (1 paper, 2016). A disease of the heart muscle or myocardium proper. "Immunoblot analysis showed that CHMP2B and BECLIN-1 protein expression were induced to variable degree in patient hearts IV.5 and IV.7 and in the other diseased hearts, indicating a similar response in cardiomyopathy of familial and idiopathic origin." (PMID 26753747, 2016).
endometriosis (1 paper, 2025). The growth of functional endometrial tissue in anatomic sites outside the uterine body. "Compared to normal human endometriosis cells, the expression of BAK1, CHMP2A, GPX4, and GSDMD was upregulated, whereas the expression of CHMP2B, IRF2, and TIRAP was negatively regulated in UCEC cells." (PMID 40535818, 2025).
familial Alzheimer disease (1 paper, 2017). A degenerative disease of the brain that causes gradual loss of memory, judgment, and the ability to function socially. "While the ESCRT-III protein CHMP2B was first genetically linked to FTD, copy number variation in CHMP2B has since been reported in a family with familial Alzheimer’s disease and genome-wide association studies for late onset AD identified an association with VPS4B." (PMID 28835279, 2017).
HIV-1 infection (1 paper, 2024). The type species of lentivirus and the etiologic agent of acquired immunodeficiency syndrome (AIDS). "To extend our understanding on the function of the CHMP2B K6 methylation in broader processes, such as HIV budding, we monitored the impact of the CHMP2B K6A and CHMP2B K6R mutants in a single round of HIV-1 infection." (PMID 38740816, 2024).
lysosomal storage disorder (1 paper, 2015). "This indicates that FTD caused by CHMP2B mutation recapitulates aspects of lysosomal storage disorder pathology." (PMID 26358247, 2015).
melanoma (1 paper, 2018). A malignant, usually aggressive tumor composed of atypical, neoplastic melanocytes. "We conclude that BAG1, CHMP2B, PEX3, and WIPI1 show a strongly different expression in melanoma vs control biopsies, according to data from 418 patients, and have never been related to melanoma according to Pubmed." (PMID 30622661, 2018). "BAG1, CHMP2B, PEX3, and WIPI1 confirm strongly different expression levels in melanoma vs healthy skin in IST Online." (PMID 30622661, 2018). "BAG1, PEX3, and WIPI1 were identified as the best three novel candidates as validated markers in both DNA and protein melanoma samples, while CHMP2B has validated differential expression at the DNA level, not observed at the protein level." (PMID 30622661, 2018).
neuroblastoma (1 paper, 2010). Neuroblastoma (NB) is the most common solid, extracranial childhood tumor. "This hypothesis is further supported by the transfection of FTD-related CHMP2B truncating mutations in neuroblastoma cell lines, which led to the formation of large vesicles, with a morphology in keeping with aberrant endosomes." (PMID 20352044, 2010).
osteosarcoma (1 paper, 2024). A usually aggressive malignant bone-forming mesenchymal neoplasm, predominantly affecting adolescents and young adults. "We observed similar results in U2OS osteosarcoma cells indicating a general requirement of SMYD2 for CHMP2B proper localization at the ICB in different cell types undergoing cytokinesis." (PMID 38740816, 2024).
periodontitis (1 paper, 2023). An acute or chronic inflammatory process that affects the tissues that surround and support the teeth. "The machine-learning method, RF, was performed to create an ideal model to predict the occurrence of periodontitis and selected five hub PRGs (CHMP2B, GZMB, ZBP1, IL1B, and IRF1)." (PMID 37090158, 2023).
preeclampsia (1 paper, 2022). Preeclampsia is a hypertensive disorder of pregnancy that is characterized by new-onset hypertension with proteinuria presenting after 20 weeks of gestation, and depending on mild or severe forms may initially present with severe headache, visual disturbances, and hyperreflexia. "CHMP2B is a part of a large complex responsible for processing cell surface receptors and has been identified as part of the placental methylation profile associated with preeclampsia." (PMID 35462239, 2022).
retinal degeneration (1 paper, 2020). Degeneration of the retina. "We previously generated a fly model of FTD-associated mutant CHMP2B neurotoxicity, in which expression of CHMP2BIntron5 but not CHMP2BWT driven by GMR-Gal4 produced a retinal degeneration phenotype characterized by a few small melanin deposits in the fly eye16." (PMID 32848189, 2020).
viral infection (1 paper, 2022). "The protein levels of these ESCRT subunits (HRS, VPS28, VPS25, CHMP2B, CHMP4B, CHMP7, VPS4A and ALIX) in the VRC were significantly increased by the viral infection in a dose-dependent manner." (PMID 35120190, 2022).
α-synucleinopathy (1 paper, 2025). "Intriguingly, a recent study identified an interaction between α-synuclein and CHMP2b in a cellular α-synuclein toxicity screen, and that disrupting this interaction was neuroprotective in a mouse α-synucleinopathy model." (PMID 40537859, 2025).
neurodegenerative disease (16 papers, 2010 to 2023). A disorder of the central nervous system characterized by gradual and progressive loss of neural tissue and neurologic function. "We have previously shown that autofluorescent lysosomal storage-like pathology is a feature of the CHMP2B mutation and is increased in microglia in CHMP2B patient frontal cortex when compared with both neurodegenerative disease and normal controls." (PMID 28093491, 2017). "These aggregates occur significantly more frequently in human CHMP2B mutation brain than in neurodegenerative disease or age-matched control brains." (PMID 26358247, 2015). "Chmp2b is the only ESCRT component associated with neurodegenerative disease and appears to be required for dendritic spine potentiation in cultured hippocampal neurons." (PMID 23284619, 2012). "Dominant negative mutations in Chmp2b cause autophagosome accumulation and neurodegenerative disease." (PMID 23284619, 2012). "Therefore, mutations in CHMP2B of the ESCRT-III subcomplex give rise to several neurodegenerative diseases because all ESCRT protein components are required for appropriate morphogenesis and function of neuronal cells." (PMID 37606396, 2023). "Importantly, we also report increased autofluorescent aggregates in the frontal cortex of FTD-3 patients with the CHMP2B mutation, when compared to neurodegenerative disease controls." (PMID 26358247, 2015). "Curiously, some mutations in autophagy-related genes and in the ESCRT-III protein CHMP2B lead to neurodegenerative diseases with accumulation of ubiquitin (66, –, 69)." (PMID 30837340, 2019). "It is proposed that mutations in CHMP2B may lead to FTD and other neurodegenerative diseases, including ALS, which is predicted to involve disruption to the cellular processes involved in the recycling and degradation of proteins." (PMID 20352044, 2010).
tumor (9 papers, 2022 to 2025). "Importantly, using immunohistochemistry analysis based on our tissue microarray, we found that CHMP2B was highly expressed in tumor tissue, and CD4 and CD8 were more likely to be positive in the CHMP2B-negative group." (PMID 38169571, 2024). "Seven pyroptosis-related genes (ELANE, IL18, CHMP2B, CHMP4C, CASP9, CHMP6, and CHMP2A) were downregulated in tumor tissues, while 31 pyroptosis-related genes were upregulated in tumor tissues." (PMID 35432539, 2022). "CHMP2B, CHMP6, and RIPK3 were downregulated, while CXCL1, GPX4, and TRAF2 were upregulated in tumor samples." (PMID 36046241, 2022).
cancer (6 papers, 2021 to 2024). A tumor composed of atypical neoplastic, often pleomorphic cells that invade other tissues. "Future studies will evaluate the CHMP2B methylation status in normal and cancer tissues to demonstrate the potential pro-oncogenic impact of ESCRT-III methylation signaling mediated by SMYD2." (PMID 38740816, 2024). "Furthermore, alternative and/or mis-splicing of ESCRT genes that affect autophagy play roles in the pathogenesis of several diseases, including TSG101 in cancer and CHMP2B and VPS4B mis-splicing in the pathogenesis of FLTD and dental dysplasia I (respectively)." (PMID 34440370, 2021). "The expression of MISP, CHMP2B, IL-18, TMSB4X, and EFEMP1 proteins in carcinoma tissue was higher than that in para-carcinoma tissues." (PMID 38835670, 2024).
infection (3 papers, 2019 to 2025). The state of being infected such as from the introduction of a foreign agent such as serum, vaccine, antigenic substance or organism. "Chmp4B RNA was unchanged during the course of the infection, while Chmp2B mRNA was significantly increased at 12 dpi (lower middle)." (PMID 30837340, 2019). "Approximately 21% to 26% of LdLPVs positively displayed CHMP2B-mCherry or CHMP4B-mCherry at 24,48 and 72 hours after infection." (PMID 40956840, 2025).
CHMP2B also shares sentences with these, for which no sentence is quoted: Parkinsonism (6 papers); Neurological Disorder (3); tauopathies (3); cognitive decline (2); hereditary spastic paraplegia (2); pancreatic cancer (2); Atrophy (1); breast tumors (1); cataract (1); Chromosome 3-linked frontotemporal dementia (1); COVID-19 (1); endometrial carcinoma (1); genetic disease (1); glioma (1); heart failure (1); inclusion myopathy (1); language disorder (1); liposarcoma (1); movement disorder (1); Myoclonus (1); myxofibrosarcoma (1); myxoid liposarcoma (1); neuromuscular disease (1); pancreatic adenocarcinoma (1); Pick disease (1); prion disease (1); prostate carcinoma (1); Sepsis (1); Spastic paraplegia (1); spinocerebellar ataxia (1).